ADH1B (alcohol dehydrogenase 1B (class I), beta polypeptide)
Diseases named in the same sentence as ADH1B in open-access papers (continued):
Sharing a sentence is not in itself a finding about the gene and the disease.
cancer (61 papers, 2009 to 2025). A tumor composed of atypical neoplastic, often pleomorphic cells that invade other tissues. "Similar estimates were obtained when using the ADH1B variant only, with an OR of 1.01 (95% CI 0.85, 1.19, p = 0.95) for any cancer and 1.01 (95% CI 0.66, 1.56, p = 0.96) for any gastrointestinal cancer." (PMID 41398582, 2025). "The levels of ADH1B transcripts were associated with the control of metabolism, cell cycle, DNA repair, and pathways related to cancer." (PMID 38256214, 2024). "Carriers with the both ADH1B rs1229984 TC/CC and ALDH2 rs671 GA/AA genotypes had a higher risk of cancer than those with the both ADH1B rs1229984 TT and ALDH2 rs671 GA/AA genotypes." (PMID 35670037, 2023). "We found that ADH1B rs1229984 was significantly associated with a variety of alcohol‐related phenotypes and cancers." (PMID 35670037, 2023). "This hospital‐based study demonstrated that ADH1B rs1229984 appears to have a stronger effect on alcohol‐related disorders and simultaneously is associated with a higher risk of alcohol‐related cancers." (PMID 35670037, 2023). "The ADH1B (Alcohol Dehydrogenase 1B (class I) has been explored in many studies, which is closely associated with alcohol metabolism, liver function and cancer." (PMID 37540213, 2023). "The ADH1B rs1229984 C allele was found to be significantly associated with alcohol‐related cancers in the Taiwanese population." (PMID 35670037, 2023). "Using data from the prospective China Kadoorie Biobank (CKB), we investigated the associations of ALDH2‐rs671 and ADH1B‐rs1229984 with total and common site‐specific cancers in 151 000 Chinese adults." (PMID 35048370, 2022). "Existing studies have shown that the expression levels of ALDH, ADH1B and the risk of poor prognosis of cancer were negatively correlated, and the high level of ALDH, ADH1B expression also implied a higher survival rate of MPM patients." (PMID 36523602, 2022). "Epidemiologic studies have extensively explored the association between ADH1B Arg47His polymorphism and cancer risk." (PMID 30872408, 2019). "Ultimately, 64 articles investigating the association between ADH1B Arg47His polymorphism and cancer risk were included in the final meta-analysis." (PMID 30872408, 2019). "It was noteworthy that we found that ADH1B Arg47His polymorphism was associated with decreased cancer risk amongst Asians while increased cancer risk amongst Caucasians." (PMID 30872408, 2019). "Overall, ADH1B Arg47His polymorphism was associated with a decreased risk of overall cancer under all the five genetic models." (PMID 30872408, 2019). "Stratified analysis by ethnicity revealed that ADH1B Arg47His polymorphism reduced cancer risk amongst Asians and mixed ethnicity group but increased risk amongst Caucasians." (PMID 30872408, 2019). "In conclusion, our meta-analysis suggested that ADH1B Arg47His polymorphism was significantly associated with decreased overall cancer risk." (PMID 30872408, 2019). "The ADH1B gene and its alleles, Arg48His (rs1229984) and Arg370Cys (rs2066702), are associated with alcohol metabolism and drinking behavior, cancer, and human phenomes." (PMID 28536537, 2017). "Esophageal cancer is associated with an Arg/Arg genotype of ADH1B Arg48His, although its 48His allele has been proved to have a protective effect against this type of cancer." (PMID 28536537, 2017). "The gene ADH1B shows several polymorphisms and has been associated with the risk of different cancers." (PMID 28805741, 2017). "Two studies in Asian populations found a significantly higher risk of cancer of upper aerodigestive tract, oral cavity, and hypopharynx in moderate or heavy drinkers carrying ADH1B*1/*1 genotype than those carrying ADH1B*1/*2 or ADH1B*2/*2." (PMID 28805741, 2017). "ADH1B genotypes have also been assessed in a case-cohort study embedded into the prospective Danish Diet Cancer and Health Study, for which we were unable to obtain risk estimates." (PMID 22363810, 2012).
cancer (continued). "The results revealed effect modifications by these polymorphisms for several types of cancer in individuals expected to be rapidly or extensively exposed to acetaldehyde due to the presence of ADH1B and/or ALDH2 gene polymorphisms." (PMID 19667493, 2009). "Notably, RRM2 and ADH1B, two genes which belong to PCUGs and PCDGs, respectively, were identified as robust pan-cancer diagnostic biomarkers." (PMID 39884577, 2025). "Strikingly, we identified that RRM2 and ADH1B are upregulated and downregulated, respectively, in all 13 cancer types, suggesting that this pair of genes could serve as promising pan-cancer diagnostic biomarkers." (PMID 39884577, 2025). "•RRM2 and ADH1B were emerged as robust pan-cancer diagnostic biomarkers." (PMID 39884577, 2025). "Furthermore, in colon cancer, loss of ADH1B in cancer-associated fibroblasts is linked to an increase in the tumor-promoting cytokine IL-6." (PMID 40508111, 2025). "However, the reported risks of alcohol‐associated cancers related to ADH1B rs1229984 and ALDH2 rs671 in East Asians are inconsistent, and heterogeneity in distinct studies has been substantial." (PMID 35670037, 2023). "Therefore, we performed an updated meta-analysis including the most recent and relevant studies to clarify the association between ADH1B Arg47His polymorphism and the overall cancer risk, involving 66 studies with 31999 cases and 50964 controls." (PMID 30872408, 2019). "However, no meta-analyses have ever investigated the association between ADH1B Arg47His polymorphism and overall cancer risk, including other types of cancer." (PMID 30872408, 2019). "ADH1B mutations have been extensively studied and have been linked to various types of cancer." (PMID 29861857, 2018). "In particular, a gene-environment interaction between ADH1B polymorphism and alcohol-drinking was significant (p = 0·035): risk of cancer of the upper aerodigestive tract in heavy drinkers with a ADH1B*1/*1 genotype was higher than for heavy drinkers carrying the ADH1B*2 allele." (PMID 21211041, 2011). "Overall, the results obtained for ADH1B polymorphisms do not concord with the so-called acetaldehyde hypothesis that the ADH1B*1 allele (which encodes a less-active enzyme, leading to lower acetaldehyde exposure) should decrease the risk of cancer in drinkers." (PMID 21211041, 2011). "In addition, ADH1B expression could result in high blood acetaldehyde levels, which can easily give rise to DNA damage, and finally cause the cancer occurrence." (PMID 27450204, 2016). "ADH polymorphisms correlate with cancer risk, and they encompass three gene loci (ADH1A, ADH1B, ADH1C) containing genetic variations that elevate cancer risk, particularly with heavy alcohol consumption." (PMID 41148854, 2025). "Ribonucleotide reductase regulatory subunit RRM2 is highly expressed, whereas alcohol dehydrogenase ADH1B is underexpressed across all 13 cancer types." (PMID 39884577, 2025). "Pan-cancer dysregulated genes and proteins were identified to develop diagnostic, pathologic, and prognostic models, with RRM2 and ADH1B emerging as robust diagnostic biomarkers." (PMID 39884577, 2025). "The magnitude of differential expression of RRM2 and ADH1B in each cancer type was presented based on proteomic and transcriptomic data sourced from CPTAC as well as transcriptomic data from TCGA-GTEx." (PMID 39884577, 2025). "Downregulation of ADH1B has been observed in some types of cancer, e.g., gastric, colorectal, and lung, where the reduction of atRA contributes to alterations in cell proliferation and death." (PMID 40508111, 2025). "These included CALB1, AURKB, SEPT14, and the histone-coding gene HIST1H1B and downregulated ADH1B and C7 in 11 cancer types." (PMID 38763334, 2024). "Our findings provide strong evidence of additive and synergic risks of ADH1B and ALDH2 variants for alcohol‐related disorders and cancer." (PMID 35670037, 2023).
cancer (continued). "The ratio of cancer in larynx, pharynx, and nasal cavities was also significantly higher in ADH1B rs1229984 CC genotype (2.33%, p = 0.004)." (PMID 35670037, 2023). "In this work, we identified the relationship between the presence of ADH1B+ CAF subpopulation in the cancer tissue and LUAD aggressiveness at an early stage of tumor progression." (PMID 37848457, 2023). "Here, we performed a large‐scale hospital‐based case–control study to explore the associations of ADH1B and ALDH2 variants with the risks of alcohol‐related disorder and cancer." (PMID 35670037, 2023). "The aim of the research was to evaluate the associations of ADH1B rs1229984 and ALDH2 rs671 with the risks of alcohol‐related disorder and cancer." (PMID 35670037, 2023). "ADH1B is related to many phenotypic traits, including alcohol metabolism, liver function, and cancer." (PMID 37324256, 2023). "In conclusion, in Chinese men ALDH2‐rs671 G>A and ADH1B‐rs1229984 G>A genotypes were associated with lower risks of overall and IARC alcohol‐related cancers, mainly UADT cancers." (PMID 35048370, 2022). "Despite the fact that CRISP3 expression has been linked to the genesis and progression of prostate and breast malignancies, CRISP3 exhibited non-significant expression in pan-cancer tissues, and ADH1B has been verified in cancer; therefore, CLU was selected." (PMID 36685863, 2022). "Many studies have demonstrated that the genetic effect of ADH1B and ALDH2 increase the risk of different types of cancers." (PMID 34680942, 2021). "We discovered that ADH1B overexpression leads to a more infiltrative cancer cell phenotype, promotes metastasis, increases the adhesion of cancer cells to mesothelial cells, and increases extracellular matrix degradation." (PMID 29861857, 2018). "Our preclinical data show that ADH1B upregulation promotes tumor progression and cancer cell invasiveness." (PMID 29861857, 2018). "First, we plated spheroids of ADH1B-overexpressing cells or spheroids of control cancer cells on the mesothelial layer and assessed the time to achieve 80% clearance of mesothelial cells for each group." (PMID 29861857, 2018). "ADH1B-overexpressing cells achieve mesothelial clearance faster than other cancer cells do and thus can easily infiltrate the peritoneal cavity." (PMID 29861857, 2018). "Live cell imaging revealed that ADH1B-overexpressing cancer cells efficiently cleared the mesothelial cell layer compared to control cells." (PMID 29861857, 2018). "The results of our live cell imaging studies demonstrate the dynamic process of cancer cells’ clearance of the mesothelial cell layer and the importance of ADH1B in this process." (PMID 29861857, 2018). "Although the up-regulation of GPX2 by the Wnt pathway had been reported, this is the first instance of a deregulation in cancer for ADH1B mRNA." (PMID 28962550, 2017). "Polymorphisms of the alcohol dehydrogenase (ADH1B Arg48His) and aldehyde dehydrogenase (ALDH2 Glu487Lys) genes are commonly associated with alcohol consumption and cancer." (PMID 28536537, 2017). "Preliminary evidence, on the other hand, shows that the risk for this cancer is different for people of Asian origin, because of genetic polymorphisms – most importantly the aldehyde dehydrogenase 2 (ALDH2) and alcohol dehydrogenase 1B (ADH1B) polymorphisms." (PMID 26229204, 2015). "Among the 1001 ESGG cases and the 1391 controls with DNA samples, genotyping was successful in 1001 (100%) cancer case and 1391 (100%) controls for ADH1B rs1229984." (PMID 24485404, 2014). "SNPs in this region (i.e. rs1229984 [ADH1B], rs1789924 [ADH1C] and rs971074 [ADH7]) have previously been associated with overall UADT cancer." (PMID 22662130, 2012).
cancer (continued). "The aberrant expression of RRM2 and ADH1B across all 13 cancer types prompted us to explore whether they can server as pan-cancer diagnostic markers to distinguish between normal and tumor samples." (PMID 39884577, 2025). "Both RRM2 and ADH1B showed excellent diagnostic performance across all cancer types tested except STAD and PAAD, supporting the potential of this pair of genes as pan-cancer diagnostic biomarkers to distinguish between normal and tumor tissues." (PMID 39884577, 2025). "In pan-cancer tissues, ADH1B expression is significantly downregulated." (PMID 41001025, 2025). "Next, the prognostic value of RRM2 and ADH1B was also explored in cancer." (PMID 39884577, 2025). "We could not obtain itemized data on cancer metastasis, which limited further investigations of the roles of ADH1B and ALDH2 polymorphisms in the cancer progression and prognosis." (PMID 35670037, 2023). "Among compounds targeting ADH1B, alcohol intake was negatively associated with PTC cancer risk." (PMID 37324256, 2023). "The expression of ADH1B was distinctly downregulated in tumor tissues of pan-cancer." (PMID 37229243, 2023). "In this hospital‐based case–control study, we determined the importance of the ADH1B rs1229984 C allele and ALDH2 rs671 A allele with regard to their association with a high risk of cancer of the larynx, pharynx, hypopharynx and nasal cavities, esophagus, and pancreas." (PMID 35670037, 2023). "The expression level of ADH1B was distinctly downregulated in tumor tissue of each cancer type." (PMID 37229243, 2023). "We subsequently compared the expression of ADH1B in pan-cancer." (PMID 37229243, 2023). "The next question to be analyzed was whether ADH1B expression in LUADs correlates with anti-cancer immune response." (PMID 37848457, 2023). "In contrast to the ALDH2‐rs671‐alcohol interactions observed, we found no clear interactions between alcohol consumption and ADH1B‐rs1229984, or between the two genetic variants, on cancer risks, which were largely consistent with previous studies." (PMID 35048370, 2022). "In addition, CD44 and CD47, which we found to be upregulated after ADH1B upregulation, help in metastasis by promoting cancer cells’ adhesion to peritoneum." (PMID 29861857, 2018). "Moreover, gene array analysis revealed that ADH1B affects several pathways related to the migration and invasion of cancer cells." (PMID 29861857, 2018). "We then investigated the effects of various factors on ADH1B expression in cancer cells." (PMID 29861857, 2018). "Additionally, the regulation of the actin cytoskeleton pathway was notably represented, suggesting that ADH1B may influence cancer cell motility and metastasis." (PMID 41001025, 2025). "The Flow char for selection of the study population (A), and the PheWAS Manhattan and QQ plots for ADH1B rs1229984 (B) and ALDH2 rs671 (C), respectively Brief Summary Our findings provide evidence of additive and synergic risks of the ADH1B and ALDH2 variants for alcohol‐related disorder and cancer." (PMID 35670037, 2023). "A comprehensive assessment of the interplay between ALDH2‐rs671, ADH1B‐rs1229984 and alcohol consumption on risks of different cancer types in a large‐scale population‐based cohort study may provide valuable insights into the aetiological role of alcohol on different cancers." (PMID 35048370, 2022). "Furthermore, there were also some studies suggesting that the influence of ADH1C polymorphism on cancer risk was independent of that of ADH1B in both European and Asian populations." (PMID 22675424, 2012). "For instance, decreased ADH1B and ADH4 expression in tumor cells can lead to acetaldehyde accumulation, which can promote cancer, DNA damage, and tumor growth." (PMID 41031088, 2025). "A contrasting pattern of similarity emerges among carcinomas originating from uterine, pulmonary, and hepatic tissues, where genes like CTHRC1, ADH1B, GHR, DES, SFRP1, and RNF150 share similar weights." (PMID 39596491, 2024).
cancer (continued). "Alcohol dehydrogenase-1B (ADH1B), as alcohol metabolizing genes, was differentially downregulated in many types of cancers, which exists glucose metabolism (Warburg Effect)." (PMID 37391825, 2023). "The common (pan-cancer) genes are MMP11 (+), C7 (-), ANGPTL1 (-), UBE2C (+), IQGAP3 (+) and ADH1B (-)." (PMID 36802377, 2023). "From our analysis, we found that the effects of ADH1B and ALDH2 are not limited to cancer onset, but also contribute to cancer prognosis." (PMID 37706329, 2023). "The expression of 24 FAM-related pathway genes was more active in para-cancer tissues than that in LUAD tissues, such as ACAA1, ACAT2, and ADH1B." (PMID 37920207, 2023). "The same authors also correlated the decreased expression of ADH1B and ADH1C with advanced stages of colorectal carcinomas, overall indicating that dysregulation of the ATRA biosynthesis can be responsible of the cancer progression." (PMID 32012980, 2020). "We analyzed control and ADH1B overexpressing cells with qRT-PCR for the expression of such genes and found that ADH1B overexpression increases CD44 and CD47 expression in the cancer cells (p < 0.001 and p < 0.001)." (PMID 29861857, 2018). "We found that cells with ADH1B expression secrete MMP-7, CD-26, and cathepsins, which promote cancer progression by their action as proteases." (PMID 29861857, 2018). "Our results are consistent with a previous study that observed class I ADH (including ADH1A, ADH1B and ADH1C) to be more highly expressed, at both mRNA and protein levels, in normal breast tissues from cancer-free women than in invasive breast tumor tissues." (PMID 28899409, 2017). "For ADH1B‐rs1229984, no clear interactions with alcohol consumption on cancer risks were observed among male current regular drinkers." (PMID 35048370, 2022). "All these findings together suggested that ADH1B, LAG3, and HAVCR2 were significantly down-regulated in cancer tissues, which would offer a good prospect that targeted ADH1B could increase the therapeutic efficacy of OV patients." (PMID 35756990, 2022). "Genes ADH1B and PDHA2 were differentially expressed in most of the 12 types of cancer and five pairs of genes exhibited consistent correlation changes (from strong correlations in normal controls to weak correlations in cancer patients) across all types of cancer." (PMID 34163562, 2021). "Similarly, no report was available for the regulation of ADH1C mRNA in cancer, and it showed no integration into our network except a physical interaction with ADH1B." (PMID 28962550, 2017).